ADAM10 (ADAM metallopeptidase domain 10)
Diseases named in the same sentence as ADAM10 in open-access papers (continued):
Sharing a sentence is not in itself a finding about the gene and the disease.
pancreatic cancer (18 papers, 2013 to 2025). "In patients with lung or pancreatic cancer, ADAM10 expression was significantly associated with overall survival." (PMID 37422628, 2023). "More importantly, ADAM9 and ADAM10 expression have also been reported to be associated with various human cancers, including pancreatic cancer and lung cancer." (PMID 29416721, 2018). "ADAM10-mediated cleavage of the Eph receptor ligand ephrin-B2 has been linked to fibrosis in pancreatic cancer, with radiation therapy shown to enhance ADAM10 expression on tumour cells and its cleavage of ephrin-B2 from stromal fibroblasts, thereby promoting tumour survival and fibrosis." (PMID 40427200, 2025). "Regarding the expression of ADAM10 on tumor cell lines of different origin, we observed the highest levels of ADAM10 on the Hodgkin’s lymphoma cell line L428 and on leukemic Jurkat variants, followed by myeloma and pancreatic carcinoma cells." (PMID 24130797, 2013). "High ADAM10 expression in pancreatic tumours correlates with a poor prognosis, indicating a role in tumorigenesis." (PMID 40427200, 2025). "circ_0000977 was shown to sequester miR-153 and relieve the repression of HIF1α and ADAM10 mRNA in pancreatic cancer cell line Panc-1." (PMID 39403602, 2024). "Collectively, the circ_0000977/miR-153/HIF1α/ADAM10 ceRNA network represents a novel mechanism contributing to the hypoxia-mediated immune escape of pancreatic cancer cells." (PMID 39403602, 2024). "For instance, RT can promote the expression of ADAM metallopeptidase domain 10 (ADAM10) in pancreatic cancer cells, leading to the cleavage of ephrinB2, which is expressed in stromal fibroblasts." (PMID 36139006, 2022). "Gemcitabine showed anti-cancer effect by down-regulating NK cells function via inhibition of ADAM10 expression and shedding of sULBP2, which broadens our previous understanding of gemcitabine in the treatment of pancreatic cancer." (PMID 27602753, 2016). "In the present report we describe the release of high levels of the ectodomain of Fat1 cadherin into the secretomes of human pancreatic cancer cells in vitro, a process that is mediated by ADAM10." (PMID 24625754, 2014). "Fat1 and its sheddase ADAM10 are overexpressed in pancreatic adenocarcinomas and ectodomain shedding is also recapitulated in vivo leading to increased Fat1 serum levels in some pancreatic cancer patients." (PMID 24625754, 2014). "In light of the fact that significant overexpression of Fat1 and of its sheddase ADAM10 appears to be common in human pancreatic cancer it came as a surprise that the subpopulation of patients with increased levels of soluble Fat1 is restricted." (PMID 24625754, 2014). "Treatment of Paca44 and Panc1 pancreatic cancer cells with ADAM10 specific siRNA duplexes resulted in >90% knockdown of ADAM10 protein levels stable for 96 h." (PMID 24625754, 2014). "Interestingly, in pancreatic cancer FAT1 was shown to be overexpressed on the surface of cancer cells together with ADAM10 metalloprotease, which mediates FAT1 ectodomain shedding." (PMID 30416985, 2018). "The results indirectly confirmed that the effect of gemcitabine on pancreatic cancer may be related to ADAM10 and ULBP2." (PMID 27602753, 2016). "In silico analysis of publically available expression array data was used to determine whether Fat cadherins and ADAM10 were also expressed in pancreatic cancer tissues; Oncomine (Compendia Bioscience, Ann Arbor, MI) was used for analysis and visualization." (PMID 24625754, 2014). "Therefore the overexpression of Fat1 in concert with the apparent overexpression of the enzyme largely responsible for its cleavage (ADAM10) appears to provide some explanation for the abundance of the Fat1 protein in pancreatic cancer cell secretomes." (PMID 24625754, 2014). "In pancreatic cancer, hypoxia is known to induce HIF1, ADAM10, and sMICA, thus leading to reduced NKG2D in natural killer (NK) cells and immune escape of tumor cells." (PMID 39403602, 2024).
pancreatic cancer (continued). "On the contrary, ADAM10 expression was induced by ionizing radiation, which led to the remodeling of the TME by ephrinB2 cleavage and resistance of pancreatic cancer to RT." (PMID 37495855, 2023). "In the TME of pancreatic cancer, hypoxia induces the overexpression of circ0000977, increases the expression of HIF1A and ADAM10, enables tumor cells to avoid immune surveillance and suppresses the lethal effect of NK cells on pancreatic cancer cells." (PMID 36238299, 2022). "circ_0000977 in pancreatic cancer can adsorb miR-153 to affect the expression of HIF1A and ADAM10 as well as regulate the immune escape of pancreatic cancer cells mediated by HIF1A." (PMID 33937077, 2021). "The present study sheds light on previously unrecognized effects of gemcitabine on tumor immune response, modulating ADAM10 and ULBP2 shedding, thus suggesting its use in chemoimmunotherapy against human pancreatic cancer." (PMID 27602753, 2016). "In a murine model for pancreatic cancer, the authors attributed the observed increased EGF secretion of organoid tumor cultures to ligand shedding, mediated by NRF2-dependent stimulation of the ADAM10 metalloprotease." (PMID 33916908, 2021). "The observations suggest that ADAM10 may serve as a potential therapeutic target for treatment of pancreatic cancer patients who are not sensitive to gemcitabine." (PMID 27602753, 2016).
lung carcinoma (17 papers, 2015 to 2025). "Overall, this study demonstrated that ADAM10 functions as a diagnostic, prognostic, and predictive biomarker for lung cancer, indicating its potential as a therapeutic target through modification of ADAM10 levels." (PMID 39991567, 2025). "On the functional front, overexpression of ADAM10 promotes lung cancer cell progression, migration, and invasion, whereas downregulation of ADAM10 inhibits these processes." (PMID 39991567, 2025). "To test the efficacy of this inhibitor in blocking ADAM10 function, we treated two lung cancer cell lines, H1299 and A549, with varying amounts of GI254023X." (PMID 39991567, 2025). "Although a previous report established that the overexpression of ADAM10 is correlated with enhanced migratory and invasive capabilities in a lung cancer cell line (A549) 11, further investigations using alternative methods to inhibit ADAM10 are needed." (PMID 39991567, 2025). "Further analysis demonstrated that the overexpression of ADAM10 leads to increases in the growth, migration, and invasion of H1299 and A549 lung cancer cells; conversely, the suppression of ADAM10 inhibits these processes in these same cells." (PMID 39991567, 2025). "Our results regarding the role of ADAM10 in lung cancer cell behavior are consistent with those reported by Guo and colleagues 11, who also reported that ADAM10 inhibits cell migration and invasion in the A549 cell line." (PMID 39991567, 2025). "Our present study demonstrated the pivotal role of ADAM10 in lung cancer progression, indicating its participation in promoting cell proliferation, migration, and invasion." (PMID 39991567, 2025). "In the present study, we observed the rapid Ca2+-dependent activation of ADAM10 in A549 lung carcinoma cells upon stimulation with ionomycin." (PMID 39497138, 2024). "Although ADAM10 mediated cadherin-11 cleavage in mouse embryonic fibroblasts and human lung cancer cells, inhibitor and short-interfering RNA (siRNA) studies indicate that the synovial fibroblast sheddase activity is ADAM- and metalloproteinase-independent." (PMID 25975695, 2015). "Also, exosomal active disintegrin and metalloproteinase domain-containing protein 10 (ADAM10) is significantly increased in patients with lung cancer and can efficiently differentiate these patients from healthy individuals." (PMID 41227214, 2025). "Although Guo and colleagues employed the lung cancer cell line A549, which has successful ADAM10 overexpression and the capacity for cell migration and invasion 11, it would be prudent to conduct further experiments utilizing two additional lung cancer cell lines, namely, H1299 and A549." (PMID 39991567, 2025). "In addition, we noticed an increase in ADAM10, which has been shown to be associated with NSCLC and a potential biomarker for lung cancer detection." (PMID 38435456, 2024). "Moreover, LCAM is also involved in the motility and invasion of lymphoma, lung carcinoma, and melanoma cells, where ADAM10 seems to be a major L1-sheddase in these tumor cell lines." (PMID 32269567, 2020). "Furthermore, analysis of ADAM10 expression variation in different clinical NSCC stages versus normal tissues revealed the substantial role of ADAM10 in the progression of lung cancer." (PMID 39991567, 2025). "Therefore, we aimed to examine how active ADAM10 might contribute to these EMT-driven changes in lung cancer development." (PMID 39991567, 2025). "In this study, we found that ADAM 10 can cleave cadherin-11 on MEFs and a lung cancer cell line, but show it does not cleave cadherin-11 on several types of primary human fibroblasts, despite detectable ADAM10 expression in these cells." (PMID 25975695, 2015). "However, the functional difference between the 180-kDa and 120-kDa fragments of Col XVII remained unclear, and the involvement of ADAM9 and ADAM10 in Col XVII shedding and in inducing EMT phenotypes in lung cancer has not been reported." (PMID 29416721, 2018).
prostate carcinoma (17 papers, 2005 to 2025). A carcinoma that arises from epithelial cells of the prostate gland. "In previous studies, the ADAM‐10 is also associated with certain type of malignancies such as the prostate cancer and pancreatic cancer." (PMID 36946281, 2023). "ADAM10 is implicated in numerous biological processes, including cell proliferation, invasion, metastasis, and cell adhesion 4-7; these functions have also been observed in prostate cancer 8, uveal melanoma progression 9, and other types of cancers." (PMID 39991567, 2025). "Our finding that ephrin-A5 is disassociated from EphA3 and released outside the cell by ADAM10 suggests that ephrin-A5 may have certain diagnostic value in prostate cancer metastasis." (PMID 35551177, 2022). "In this regard, Barsoum and coworkers provided evidence that reduction of nitric oxide levels in prostate cancer cells induced the hypoxia-inducible factor 1α (HIF1α), causing augmentation of ADAM10 expression and a significant increase of MICA secretion in the extracellular milieu." (PMID 32269567, 2020). "They indicated that high APP protein levels correlate with an aggressive cancer stage, and they observed strong nuclear staining for ADAM10 in prostate cancer tissues compared to benign prostate hyperplasia." (PMID 41614805, 2025). "Three studies showed that DHT increased ADAM10 expression in prostate cancer cells and stimulated its nuclear translocation." (PMID 41614805, 2025). "Targeted inhibition of ADAM10 activity is a potential therapeutic approach for apoptosis-resistant prostate cancer." (PMID 35551177, 2022). "The hypoxia-induced circ-0000977 modulates the immune escape of prostate cancer cells via the miR-153/HIF1A/ADAM10 axis." (PMID 35840974, 2022). "A disintegrin and metalloprotease-10(ADAM10) promotes the metastasis of prostate cancer (PCa), but the specific mechanism is indistinct." (PMID 35551177, 2022). "Another member of the ADAM family, ADAM10, has been reported to be transported into the nucleus and contributes to the pathogenesis and progression of human prostate cancer." (PMID 34671207, 2021). "In prostate cancer cells, ADAM10 is highly expressed and contributes to extracellular matrix maintenance and cell invasion." (PMID 32269567, 2020). "ADAM10 has a role in androgen receptor nuclear translocation and has been shown to translocate to the nuclear and the perinuclear region during prostate cancer pathogenesis and progression." (PMID 21569301, 2011). "ADAM10 is known for its shedding activity, particularly in the release of EGFR ligands, and is upregulated in response to EGF and IGF-I, both of which are implicated in aggressive prostate cancer." (PMID 41614805, 2025). "About the relationship between ADAM‐10 and malignancy, the higher expression of ADAM‐10 may trigger the metastasis of prostate cancer via the ephrin‐A5 shedding." (PMID 36946281, 2023). "ADAM10 contributes to prostate cancer metastasis via cleaving ephrin-A5." (PMID 36922678, 2023). "It would be exhilarating that if an inhibitor of ADAM10 could be developed and applied in the clinic to decrease the mortality by reducing the metastasis of prostate cancer, which is of great significance to patients and society." (PMID 35551177, 2022). "Knockdown of ADAM10 decreased proliferation of prostate cancer cells, suggesting that ADAM10 may contribute to the progression of prostate cancer by increasing proliferation." (PMID 26912236, 2016). "Moreover, benign prostate hypertrophy (BPH) (n = 20) and prostate cancer (PC) (n = 64) tissue samples were analysed to study the correlation of ADAM10 localization with clinical parameters such as Gleason score and preoperative prostate-specific-antigen (PSA) levels." (PMID 41614805, 2025). "Several of these genes are important for prostate cancer progression including metalloproteinases ADAM9 and ADAM10." (PMID 32365491, 2020).
prostate carcinoma (continued). "Overexpression of ADAM species is known in tumor cell lines, for example, ADAM10, ADAM12 and ADAM15 in hematological malignant tumor cell lines, and ADAM9, ADAM10, ADAM15 and ADAM17 in prostate cancer cell lines." (PMID 16277668, 2005). "RT-qPCR analysis show that ADAM10, ARMC8, COMMD8, EEA1 and PPM1B were expressed at similar levels in prostate cancer cells transfected with ZBTB38 and control siRNAs suggesting that these genes are not regulated by ZBTB38, but rather co-regulated by a common upstream factor and/or pathway." (PMID 32365491, 2020). "Furthermore, interfering with the hypoxia-induced accumulation of HIF-1α and ADAM10 has been shown to enhance MICA surface expression and to reduce MICA shedding, leading to augmented cytotoxicity of PBL against DU145 prostate cancer cells under hypoxia." (PMID 23724099, 2013). "Findings on hormone regulation of ADAM10 are not completely novel, as androgen upregulation of ADAM mRNA has been previously reported in prostate cancer cells." (PMID 39837817, 2025).
colon carcinoma (15 papers, 2009 to 2025). "ADAM10 expression in colon cancer enhanced metastasis and was associated with chemoresistance." (PMID 24952873, 2014). "Most recently, a therapeutic approach using ADAM10-targeting CAR-T cells has been reported to be effective against colon cancer in vivo." (PMID 37422628, 2023). "We thus evaluated the biodistribution of mAb 8C7 in mice bearing human LIM1215 colon cancer xenografts, which we have previously shown to possess high levels of active ADAM10." (PMID 35804938, 2022). "Previous studies revealed that TIMP-1 inhibited a disintegrin and metalloprotease (ADAM)-10 activity, which regulates cancer stem-like cells and tumor growth through activation of Notch signaling in colon cancer." (PMID 30486830, 2018). "In colon cancer, overexpression of ADAM10 has been reported to correlate with an advanced stage of disease and with enhanced induction of metastasis." (PMID 27517630, 2016). "Exploiting this approach, we identified the surface membrane enzyme ADAM10 as a candidate antigen able to elicit a humoral immune response in colon cancer." (PMID 27517630, 2016). "L1 and its protease ADAM10 have been shown in colon cancer only at the invasive front, where proteolysis occurs to stimulate cell migration." (PMID 19874583, 2009). "Furthermore, expression of the associated protein sets also correlated with ADAM10 expression in human GBM and colon cancer specimens (TCGA datasets), indicating clinical relevance." (PMID 41226720, 2025). "L1 and ADAM10 mediated L1 proteolysis also induces metastasis in human colon cancer cells." (PMID 19874583, 2009). "Though the mechanism of how L1 is upregulated in metastatic tumors is still undefined, it is coincidently upregulated with ADAM10 as target genes of β-catenin/TCF signaling, with co-expression at the invasive front of colon carcinomas." (PMID 20840789, 2010). "Interestingly, the same authors provided evidence of an ADAM10-dependent FAT1 shedding in HCT15 colon carcinoma cell line, as demonstrated by the accumulation of FAT1 on the cell surface upon siRNA-mediated silencing of ADAM10 mRNA." (PMID 30416985, 2018).